CD4 (CD4 molecule)
Diseases named in the same sentence as CD4 in open-access papers (continued):
Sharing a sentence is not in itself a finding about the gene and the disease.
glioma (continued). "Activated memory CD4+ T cells have been shown to differentiate into distinct subtypes of T cells including Th1, Th2, Th17 and Treg cells and produce many cytokines that regulate the pro or anti-tumor role of CD4+ T cells during malignant biological process of glioma cells." (PMID 37779195, 2023). "In addition, the findings in this study revealed the correlation between the high CP expression in gliomas and increased infiltration of macrophages, B cells, neutrophils, dendritic cells, CD4+ T cells, and CD8+ T cells, with the help of the CiberSort and ESTIMATE algorithms and Timer portal." (PMID 37637428, 2023). "Similarly, higher CD4+T cell, M2 macrophage, neutrophil and myeloid dendritic cell infiltration also correlated with worse outcome in glioma." (PMID 37142967, 2023). "Again, these computational results await confirmation in pre-clinical mouse models of glioma to determine whether the adoptive transfer of NK cells with CD4+ T helper cells can restrict glioma tumor cell migration and invasion or possibly even progression to higher glioma grades." (PMID 34539622, 2021). "We assessed the profile of immune infiltration, and found that naïve CD4+ T cells, activated mast cells, and monocytes were protective factors, while resting memory CD4+ T cells and M1 macrophages were risk factors for the prognosis of patients with grade II and III gliomas." (PMID 34805164, 2021). "Moreover, expression of SERPINA3 correlated with low CD4+ T cell infiltration in glioma tissues." (PMID 34449972, 2021). "Minimal differences were noted in IFNγ, TNFα, Granzyme B, and CD107B expression when comparing CD4+ T cells from glioma patients before and after M032 treatment; however, a significant reduction in IL-4 production between pre- and post-M032 treatment in peripheral blood CD4+ T cells was noted." (PMID 35342877, 2021). "Similarly, CD4+ cell populations were found to be necessary for the complete efficacy of combined oncolytic herpes simplex virus (oHSV ΔG47-mIL12) and immune checkpoint inhibitor therapy in two distinct murine derived glioma models." (PMID 32914058, 2018). "Treg depletion studies in culture and in an orthotopic murine model of glioma suggested that the activity of the increased hematogenous populations of Tregs in GBM patients may be linked to Th2 responses and suppressed proliferation of CD4+ T cells." (PMID 32914058, 2018). "Interestingly, significant alterations affected by tumor progression were found in the LGG to LGG and LGG to GBM recurrence, but not for the GBM to GBM recurrence, and the changes were primarily shown in the CD4+ T cell compartment, suggesting that immune infiltrations link with glioma progression." (PMID 29643764, 2018). "In this study, we demonstrated that PC61 anti-CD25 mAb treatment of glioma bearing mice resulted in a decrease of brain-infiltrating Tregs only, whereas the CD4+ and CD8+ effector cells were increased and could exert their cytotoxic activity on the tumor cells." (PMID 23710206, 2013). "In fact, in some models, the anti-tumour activity of lysate-based vaccines is CD4+ T cell mediated, including our studies of a glioma vaccine similar to the one used here, suggesting there may be a significant cohort of CD4+ T cells capable of providing protection against DC elimination." (PMID 23734246, 2013). "The glioma microenvironment is characterized by predominant infiltration of both CD8+CD25- T cells and CD4+CD25+FOXP3+ Tregs." (PMID 41272822, 2025). "Han and colleagues compared TIM-3 expression on peripheral CD4+ and CD8+ T cells from 30 glioma patients of different grades and 30 healthy controls." (PMID 40072074, 2025). "In gliomas, animal models revealed that low‐grade gliomas (LGG) have increased infiltration of CD4+ T cells, CD8+ T cells, and NK cells, which is largely absent in high‐grade gliomas (HGG)." (PMID 40062730, 2025).
glioma (continued). "We demonstrated the effect of ADORA1 on T cells, showing that inhibition of ADORA1 in the shADORA1 group increased the recruitment of CD4+ T and CD8+ T cells to gliomas compared to the control group." (PMID 40376586, 2025). "It was recently shown, using glioma mouse models, that infiltration of CD8+ and CD4+ T cells is induced as soon as 10 days after intracranial tumor implantation." (PMID 39378431, 2025). "Overall, gliomas exhibited limited infiltration of lymphocytes such as CD8+ T cells, CD4+ T cells, and B cells, as well as antigen-presenting cells like dendritic cells, consistent with the generally immunosuppressive nature of gliomas." (PMID 40636690, 2025). "We then explored how M002 therapy affected tumor-infiltrating lymphocytes (TILs), specifically CD4+ T cells, over the course of treatment using the B6/GSC005 and B6/GL261-PVRL1 glioma models." (PMID 39885128, 2025). "In the CSF, higher fractions of activated CD4+ and CD8+ Tc as well as Bc were shared between RRMS and IDH-WT glioma patients in comparison to SD controls." (PMID 39497174, 2024). "Glioma-derived exosomes suppress CD3+ and CD4+ T-cell activation and responses by acting on monocyte maturation and formation of monocytic MDSCs rather than on direct interaction with T cells." (PMID 39267734, 2024). "Anti-TIM3 induced global changes in the immune response within the glioma, as reflected by increases in the phagocytic MG, cDC2, CD8 cytotoxic, inflammatory MG, CD4 Tcm, and monocyte populations." (PMID 39137048, 2024). "PD1 and PD-L1 expression in human gliomas appears to be predominantly present on CD8+ and CD4+ T cells, with minimal expression on glioma cells." (PMID 39766048, 2024). "Liu and colleagues demonstrated greater levels of TIM-3 expression on CD4+ and CD8+ T cells from glioma patients’ tissues (58% of which were glioblastoma) compared to healthy controls." (PMID 39513882, 2024). "The analysis shows that in glioma patients who had high levels of IGFBP5 expression, the levels of T cell CD4+ memory cells, Neutrophil cells, B cell memory cells, Macrophages, Tregs, and NK cell resting cells significantly increased." (PMID 38164271, 2024). "In the CSF, higher fractions of activated CD8+ and CD4+ Tc were observed in ALE, RRMS, IDH-WT glioma, and CNS-DLBCL patients." (PMID 39497174, 2024). "The major types of TILs found in glioma patients are CD3+, CD3+/CD8+, CD3+/CD4+, CD3+/CD4−CD−, and CD3+/CD4+ CD8+ as observed in patient-derived tumor cell lines." (PMID 39452154, 2024). "In the PB, ALE, IDH-WT glioma, and CNS-DLBCL patients shared an increase in activated CD8+ and CD4+ Tc, however, Tc activation was even more pronounced in IDH-WT glioma and CNS-DLBCL than in ALE." (PMID 39497174, 2024). "The higher intertumoral expression of TIM-3 in GBM in comparison to low-grade gliomas in CD4+ and CD8+ T cells is indicative of the contribution of TIM-3 to glioma severity in patients." (PMID 38275876, 2024). "Examination of TCGA-derived samples uncovered a notable increase in the proportion of CD4 memory-activated T cells, M1 macrophages, and M2 macrophages within the CLEC7A high-expression cohort of glioma patients." (PMID 38846954, 2024). "Among gliomas, astrocytomas showed a significant reduction in the levels of CD3+ and CD4+ lymphocytes when compared to GBM." (PMID 38816839, 2024). "There are various peripheral immune components in the glioma microenvironment, including CD8 cytotoxic T lymphocytes (CTLs), CD4 helper T (Th) cells, macrophages, myeloid-suppressor cells (MDSCs), natural killer (NK) cells, neutrophils and Treg cells." (PMID 37543576, 2023). "Myeloid-derived suppressor cells (MDSCs) have the ability to suppress the antitumor activity of NK cells and CD4+ and CD8+ T cells in the TEM of gliomas." (PMID 38275375, 2023). "In high-grade gliomas, including GBM, there is a report that the decrease in CD4-positive lymphocytes during treatment correlates with death due to early tumor progression." (PMID 37071249, 2023).
glioma (continued). "In patients with glioma, highly expressed GSDMD was negatively correlated with B cell (p < 0.0001) and CD4+ T cell (p < 0.0001) infiltrations and positively correlated with cancer-associated fibroblasts (CAFs) (p < 0.0001) and macrophages (p < 0.0001)." (PMID 37371484, 2023). "The expression of CEACAM1 on CD4+ and CD8+ T-cells in the peripheral blood of patients with glioma was significantly higher 1 week after radiotherapy than before radiotherapy and was further increased 1 month after radiotherapy." (PMID 36928507, 2023). "In a murine glioma model, CTLA-4 blockade was shown to enhance anti-tumor immunity via improved CD4+ T cell function and resistance to Foxp3+ Tregs." (PMID 36768342, 2023). "Thus, CD4+ CTLs may play an important role in antitumor immunity against gliomas." (PMID 37304294, 2023). "Most lymphoid cells in glioma tissue are CD8+ cells, whereas CD4+ “helper” cells are less abundant and the majority of these T cells lack antitumor activity." (PMID 38275375, 2023). "The results showed that PLEKHA4 expression was positively correlated with B cell, CD4+ T cell, CD8+ Tcell, macrophage cell, neutrophil cell, and dendritic cell in glioma." (PMID 36714030, 2023). "On the other hand, the fractions of regulatory T cells, activated CD4 + T cells, plasma B cells, and activated dendritic cells were significantly increased in GBM compared with grade II and III glioma." (PMID 37149563, 2023). "In patients with glioma, the expression of TIM-3 on CD4+ and CD8+ T cells is significantly higher than in healthy controls, and its expression level correlates with the grade." (PMID 37274252, 2023). "Especially in gliomas, PDCL3 expression revealed a positive correlation with M1 macrophages, M2 macrophages, CD4+ T cells, CD8+ T cells, Tregs, and dendritic cell infiltration." (PMID 37006287, 2023). "The CD8 + T-cell and naive CD4 + T-cell fractions were significantly lower in GBM than in grade II and III glioma." (PMID 37149563, 2023). "In particular, TCL+TIO3 not only induced the activation of CD4+ T, CD8+ T and NK cells but also inhibited PD1 and PD-L1 expression in multiple immune cells and glioma tissues by suppressing the expression of TGF-β2." (PMID 36776837, 2023). "Our study provides novel insights into the distribution and possible role of CD8+ and CD4+ TEMRA cells and their subsets in healthy donors and patients with high-grade gliomas and brain metastases receiving RT." (PMID 36831183, 2023). "In glioma mice, combined therapy of anti-CXCR4 and anti-PD-1 reduced immunosuppressive leukocytes counts, advanced the CD4+/CD8+ T cell ratio and raised the amount of pro-inflammatory cytokines." (PMID 37790751, 2023). "This study aimed to investigate the expression of CEACAM1 on CD4+ and CD8+ T-cells in the peripheral blood of patients with glioma before and after radiotherapy." (PMID 36928507, 2023). "The background (no peptides) IFNγ responses, summed from all three sets of the glioma patient’s PBMC, measured 0.78% ± 1.05% for CD4+ T cells and 0.016% ± 0.02% for CD8+ T cells." (PMID 36765532, 2023). "In glioma and acute myeloid leukemia, NQO1 mRNA levels were negatively correlated with CD4 T cells while positively correlated with CD8 T cells." (PMID 37583897, 2023). "To further elucidate which immune cell types confer a poor prognosis in glioma, we estimated the abundance of six immune cell types commonly present in the TME: memory B cells, naïve B cells, CD4+ T cells, CD8+ T cells, NK cells and monocytes." (PMID 36230719, 2022). "The relationship between immune infiltration and somatic CNV regarding the expression of COL6A2 in glioma, the results show that the copy number of COL6A2 has different degrees of infiltration relationship with T cell CD8+, T cell CD4+, DC, etc." (PMID 36505882, 2022). "Compared to those in the 200 randomly selected gliomas, the correlations of gp96 expression with CD8, CD4, and PD-1 expression were significantly reduced in the IPA-comparable group." (PMID 35794988, 2022).
glioma (continued). "Flow cytometry was respectively performed to detect the PD-L1 of glioma cells and programmed death protein 1 (PD-1), CD3, CD4 and CD8 in lymphocytes, as well as distribution of the cell cycle." (PMID 35765095, 2022). "More importantly, DUSP10 expression correlated positively with the infiltration of B cells, CD4+ T cells, CD8+ T cells, neutrophils, macrophages, and dendritic cells in glioma." (PMID 36713584, 2022). "Four types of glioma-infiltrating T cells, including CD8+ T, CD4+ T, Tregs, and cycling T cells, were captured and annotated by the data provider." (PMID 36276141, 2022). "They performed RNAseq analysis of TILs from resected gliomas and identified highly cytotoxic CD8+ T cells expressing KLRB1, as well as conventional CD4+ T cells." (PMID 35185935, 2022). "This survival benefit was associated with significantly increased CD45+ immune infiltrates, including CD4+ and CD8+ T cells, in S100a4−/− host gliomas." (PMID 35140215, 2022). "Flow cytometry staining also showed that a large fraction of glioma-infiltrated CD8+ and CD4+ T cells expressed CD161 while only small proportions were present in the blood of the same patients." (PMID 35185935, 2022). "These ex vivo studies are consistent with our prior results where combined PD-1 and CCR2 blockade led to decreased numbers of exhausted CD4+ and CD8+ T cells and increased IFN-γ expression within the gliomas." (PMID 36685592, 2022). "On the other hand, KDELR1 expression was associated with immune infiltration (including the infiltration of CD8+ T cells, CD4+ T cells, macrophages, and so on) and microenvironment parameters (including stromal, immune, and ESTIMATE scores) in gliomas." (PMID 35814367, 2022). "Another important finding in the current study is that MCMs expression has a positive correlation with the abundance of infiltrating B cells, CD4+ T cells, CD8+ T cells, macrophages, and neutrophils in glioma." (PMID 36465369, 2022). "Low levels of CD4+ T helper (Th) cells and CD8+ cytotoxic T lymphocytes (CTLs) within the T cell population have been shown to infiltrate gliomas." (PMID 35860278, 2022). "Triptolide-induced downregulation of glioma PD-L1 increased IFN-γ and IL-2 and reversed glioma-induced inhibition of CD4+ helper T cells." (PMID 36700235, 2022). "KDELR1 expression was positively associated with immune infiltration (including infiltration by CD8+ T cells, CD4+ T cells, macrophages, and so on) and microenvironment parameters (including stromal, immune, and ESTIMATE scores) in gliomas." (PMID 35814367, 2022). "Elevated levels of infiltrating immune cells (including CD8+ T cells, CD4+ T cells, and dendritic cells) were observed in the high DDR score glioma." (PMID 35720326, 2022). "Using TIMER database analysis, we found that alterations in the somatic copy number of NCAPG correlated significantly with infiltration of B cells, CD4+ T cells, CD8+ T cells, neutrophils, macrophages, and dendritic cells into gliomas." (PMID 35280743, 2022). "HDAC expression was significantly correlated with the infiltration of B cells, CD4+ T cells, CD8+ T cells, macrophages, neutrophils, and dendritic cells in glioma." (PMID 35359455, 2022). "APOL4 expression was positively correlated with immune infiltration (including DC cells, neutrophils, CD8+ T cells, B cells, macrophages, CD4+ T cells, etc.)and microenvironmental parameters (including immune, stromal, and ESTIMATE scores) in gliomas." (PMID 36233633, 2022). "Infiltrating immune cells are composed of microglia/macrophages, MDSCs, CD4+ T cells, regulatory T cells (Tregs), and granulocytes in the TME of gliomas." (PMID 35281087, 2022). "Collectively, BMDMs, MG, PMNs, CD4+ and CD8+ cells represent the main immune cell populations of the TME in gliomas and we analyzed their presence, in relative proportion, as a percentage of CD45+ cells." (PMID 34944798, 2021).
glioma (continued). "Through the CIBERSORT algorithm, M2, M1, and M0 macrophages, monocytes, DCs, and subsets of B and T cells (CD4+ and CD8+) were distinguished in the glioma microenvironment." (PMID 34220791, 2021). "Particularly, the ratio of CD4+ to CD8+ T cells is highly correlated to glioma grading, with higher grade gliomas (i.e., GBM) having large numbers of CD4+ T cells (>93%) compared to CD8+ T cells in the TME." (PMID 34177918, 2021). "Further, we used TIMER to analyze the relationship between GNG5 expression and infiltration abundance of six immune cells (B cells, CD4+ T cells, CD8+ T cells, neutrophils, macrophages, and dendritic cells) after purity correction in glioma." (PMID 34098960, 2021). "Use of adenovirus expressing TNFα or IFNγ into tumors enhanced infiltration of CD4+ and CD8+ T cells along with increased expression of MHCI/II on the glioma cells in vivo." (PMID 33790740, 2021). "In G422 murine glioma models, it has been shown that PDT increases the ratio of CD4+/CD8+ lymphocytes and promotes TNF-α and IFN-γ release and promotes an anti-glioma response mediated by complement C3 and T-cells." (PMID 33540759, 2021). "L19-mIL12, comprising murine IL12 fused to the L19 antibody, has a strong effect on tumour-infiltrating immune cells, increasing the infiltration and activation of CD4 and CD8 T cells in mouse glioma models." (PMID 33964937, 2021). "Secondly, the ratio of CD4+ T cells, CD8+ T cells, regulatory T cells (Treg), and other types of T lymphocytes in the glioma microenvironment was different." (PMID 35096561, 2021). "Considering the limited immune cells in the CNS system due to the BBB, neutrophils, macrophages, MDSCs, CD4+ T cells, CD8+ T cells, and Tregs were regarded as the major infiltrated immune cell types in glioma for the evaluation." (PMID 34540896, 2021). "In the glioma microenvironment, GAM perpetuate CD4+/CD8+ T cell apoptosis through secretion of CD95, the ligand for the T cell death receptor Fas, and IL-6, a potent inducer of Fas." (PMID 34884869, 2021). "A variety of immune cells including macrophages, neutrophils, CD4+ helper T (Th) cells, regulatory T (T reg) cells, CD8+ cytotoxic T lymphocytes (CTLs), and natural killer (NK) cells are present in glioma microenvironment." (PMID 33917399, 2021). "A key finding in our study is that high EVA1C expression correlates with the high abundance of immune infiltrates including B cells, CD4+ T cells, neutrophils, macrophages and DCs in WHO grade II/III glioma." (PMID 34267752, 2021). "Similar to GL26 glioma, elevated glucose uptake and mitochondrial mass were detected in the tumor-infiltrating CD8+ or CD4+ T-cells with the T+H combination therapy (p < 0.05)." (PMID 33391535, 2021). "Tumor-infiltrating lymphocytes, including CD4+ and CD8+ cells, are also found in glioma, and their levels are correlated with patient survival." (PMID 33902005, 2021). "Although scarce, there is a lymphocytic infiltrate in high-grade gliomas, which include CD4+ T helper (Th), CD8+ and CD4 Tregs (CD4+CD25+Foxp3+) cells." (PMID 32570988, 2020). "Lymphoid cells were present in glioma regions showing prominent SH activity and TAMRA-FP hotspots partially overlapped with CD4- and CD8-positive cells, whereas TAMRA-FP hotspot clusters sparsely expressed the T-cell markers." (PMID 32190011, 2020). "CD4+ and CD8+ TILs isolated from intracerebral GL261 gliomas showed high A2aR expression levels, similar to the observations made during profiling of human gliomas." (PMID 32721947, 2020). "Quantification of immune cells (CD20+ B cells, CD4+ T cells, CD8+T cells, CD68+ Macrophages, and CD163+ TAMs) in our 304 glioma cases (WHO I–IV)." (PMID 32528967, 2020). "Overall, we envisage that the lower expression of C5AR1 in NL gliomas, by impacting negatively on MSR1-expressing M2 phenotype macrophages and positively on NK and CD4+/CD8+ T cells, favors anti-inflammatory and anti-tumoral cell signaling cascades." (PMID 33059718, 2020).